BRCA1 (BRCA1 DNA repair associated)
Diseases named in the same sentence as BRCA1 in open-access papers (continued):
Sharing a sentence is not in itself a finding about the gene and the disease.
ovarian carcinoma (continued). "cfDNA analysis in ovarian cancer can be used for early detection, disease monitoring, determining response to treatment and detection of minimal/molecular residual disease (MRD) and for identification of specific genetic alterations, such as BRCA1/2 mutations, that may be present in ovarian cancer." (PMID 40391215, 2025). "These include AIF1, CD8A, and BST1 in ovarian cancer BRCA1-mutant cancers, and SEC61A2 and IGFBP3 in BRCA2-mutant ovarian cancer." (PMID 40647506, 2025). "Due to limited evidence of screening for ovarian cancer, ESMO guidelines recommend RR-BSO at ages 35–40 years for BRCA1 carriers and 40–45 years for BRCA2 carriers." (PMID 40974500, 2025). "PARP inhibitors have shown success in the treatment of BRCA1/BRCA2 mutant malignancies, particularly in breast and ovarian cancers." (PMID 40076468, 2025). "Promoter hypermethylation of key HRR genes, especially BRCA1 and RAD51C, can silence gene expression and induce HRD, with prevalence reaching up to 60% in TNBC and 1–15% in ovarian cancer." (PMID 40864792, 2025). "To address if ZC3H18’s transcription related functions are independent of its replication related functions, we depleted ZC3H18 and assayed the abundance of transcripts of BRCA1, a gene known to be transcriptionally upregulated by ZC3H18 in ovarian cancers." (PMID 40354417, 2025). "Recently, BRCA1/2 gene testing has become available for identifying therapeutic targets, such as PARP inhibitors, for patients with breast and ovarian cancer." (PMID 40249378, 2025). "According to the findings of this study, assessing the levels of BRCA1 gene expression and CA15-3 tumor marker in BC patients, particularly those with a family history of breast or ovarian cancer, is crucial." (PMID 39742378, 2024). "The use of PARP inhibitors, particularly in BRCA1- and BRCA2-mutant ovarian cancers, has revolutionized the management of these patients and has been one of the most successful achievements in the last decade in the field." (PMID 39028933, 2024). "Above all, BRCA1 (breast cancer gene 1) and BRCA2 (breast cancer gene 2) are the most common contributors to breast/ovarian cancers." (PMID 38279352, 2024). "Germline BRCA1 and BRCA2 testing for clinically indicated breast and ovarian cancer patients has proven cost-effective worldwide and in Thailand16–18." (PMID 38355628, 2024). "Most recently, its inhibition was found to increase the sensitivity of HRR proficient ovarian cancers to PARPi by downregulating RAD51 and BRCA1/2." (PMID 39638799, 2024). "Here, we use data from 572 families from Malaysia and Singapore with BRCA1 and BRCA2 PVs to estimate age-specific relative and absolute breast and ovarian cancer risks." (PMID 38333895, 2024). "BRCA1 and BRCA2 PVs confer increased risks of prostate, pancreatic, and ovarian cancers, while moderate-to-high risks of pancreatic (OR 4.21), prostate (OR 2.58), and gastric (OR 2.97) cancers were estimated for ATM-variant carriers." (PMID 38929805, 2024).
ovarian carcinoma (continued). "For BRCA1/2-related and BRCAWT patients with ovarian cancer brain metastasis treated with olaparib or niraparib as maintenance therapy, PFS ranged from 9 months to 4 years." (PMID 39201718, 2024). "Studies have shown that high methylation levels of BRCA1 and RASSF1A are prevalent in ovarian cancer patients, with 82% of patients exhibiting the same high methylation pattern in serum or plasma BRCA1 and RASSF1A." (PMID 39345884, 2024). "BRCAPro is a Bayesian computer program or statistical model for calculating an individual’s probability of being a carrier of BRCA1/BRCA2 PGVs, based on the type of cancer and history of BC and/or ovarian cancer among relatives of the first and second degree." (PMID 38672070, 2024). "While studies over the last decade have reported BRCA1 epimutations in white blood cells (WBC) from breast and ovarian cancer patients, the potential hazard ratio for incident TNBC and HGSOC was not formally assessed until recently." (PMID 40225940, 2024). "While current evidence suggests that STIC could act as a precursor for ovarian carcinoma in high-risk women with inherited BRCA1 or BRCA2 mutations, the clinical significance of STIC is not as well-defined in women from the general population, where 85–90% of all HGSC originate." (PMID 39594243, 2024). "Many clinical trials, including trials evaluating drugs targeting ATR, ATM, WEE1, checkpoint kinase 1/2 (CHK1/2), BRCA1/2 and RAD51, have been designed to evaluate interference with DDR pathways to overcome platinum and PARPi resistance in ovarian cancer." (PMID 38539161, 2024). "In that study, among 20 heavily pretreated, mostly platinum-resistant, ovarian cancer patients with prior PARP inhibitors (PARPi), four with germinal LoF alterations in BRCA1 and RAD51C genes attained PRs32." (PMID 38555285, 2024). "Germline variants were very rare and the only two genes with more than 2% prevalence in the patient cohort where BRCA1 and BRCA2, which was identified in ovarian cancer." (PMID 39277826, 2024). "We knocked down BRCA1 and BRCA2 in ovarian cancer cells and treated them with olaparib in the presence or absence of HMGA1‐knockdown." (PMID 39690136, 2024). "In this study, we assessed the contribution of BRCA1 and MGMT epimutations to breast and ovarian cancer in women from Saudi Arabia." (PMID 38542081, 2024). "Our study identified a significant correlation between BRCA1 gene expression and CA15-3 tumor marker levels among individuals with a history of breast and ovarian cancer." (PMID 39742378, 2024). "This economic evaluation found that population-based BRCA1, BRCA2, and PALB2 testing among unselected women was cost-effective for the prevention of breast and ovarian cancer and remained cost-effective in extensive 1-way sensitivity analyses." (PMID 38353949, 2024). "The determination of the HRD status is now mandatory for any high-grade ovarian cancer and can be obtained by CGP testing of BRCA1 and BRCA2 and genomic instability score." (PMID 37932736, 2023). "Specific genetic tests on BRCA1/BRCA2 status are available and work well for ovarian cancer, but only a small fraction (about 10%) of ovarian cancers are associated with those variants." (PMID 36981032, 2023). "CircPLEKHM3 regulated the expression of miR-9, BRCA1, KLF4, Akt1, DNAJB6 and performed a tumor suppressive function in ovarian cancer." (PMID 38152652, 2023). "The sister of PN3 (p.D1778Gfs*27 heterozygote) had breast/ovarian cancers at around 10 years older than the age PN3 developed cancer, possibly suggesting a worsened HBOC (BRCA1) phenotype due to compound heterozygosity." (PMID 38146508, 2023). "Of the 2005 BRCA1 and 1999 BRCA2 carriers, six and three cases of ovarian cancer were diagnosed, respectively, between 30 and 34 years." (PMID 36894311, 2023).
ovarian carcinoma (continued). "A previous study has shown that inhibiting USP1 can reduce the viability of BRCA1/2 mutant cancer cells (e.g. ovarian cancer cells), thereby USP1 is a SL partner of BRCA1 and has been a promising drug target in clinical cancer therapy." (PMID 37387166, 2023). "The possible utility of 2c in ovarian cancer can also be related to its activity on AKT molecules, which have already been related to patients’ survival, tumor morphology and BRCA1 expression." (PMID 37108391, 2023). "It is known that BRCA1 and BRCA2 are tumor suppressor genes involved in DNA repair, which are closely related to the incidence of ovarian cancer." (PMID 36611214, 2023). "Next, we evaluated the activity of PRT543 in an ovarian cancer PDX model which had acquired resistance to olaparib (CTG-1086, BRCA1 deleted)." (PMID 37861290, 2023). "Next, we examined the changes of BRCA1, BRCA2, ATM, and RAD51, key genes of HR repair pathway, in MEnZn‐CuO NPs‐treated ovarian cancer cells." (PMID 37206208, 2023). "Our findings indicated that female relatives of BRCA1 and BRCA2 carriers are at increased risks for breast and ovarian cancers." (PMID 36861435, 2023). "Other reported targets are HSP90 and VEGFR3 shown to attenuate RAD51, BRCA1, and BRCA2 expressions in ovarian cancer." (PMID 37370140, 2023). "Breast and ovarian cancer cluster regions (BCCR and OCCR, respectively) have been mapped on both BRCA1 and BRCA2 genes." (PMID 38203374, 2023). "Notably, the cohort of recurrent platinum-resistant ovarian cancer in TOPACIO indicated that the ORR among patients with or without BRCA1/2 mutations or homologous recombination deficiency (HRD) seemed to be similar (BRAC1/2-mutation: 18%, BRCA1/2-wt: 19%; HRD positive: 14%, HRD negative: 19%)." (PMID 37345194, 2023). "To estimate the actual prevalence of pathogenic/likely pathogenic germline indels, we carried out a systematic analysis of BRCA1 and BRCA2 tumour sequencing data at homopolymeric stretches, in a cohort of consecutive high-grade ovarian cancer (HGOC) patients." (PMID 37179432, 2023). "Finally, germline mutations in Breast Cancer Gene 1 (BRCA1), Breast Cancer Gene 2 (BRCA2), BRCA1 interacting Protein 1 (BRP1), Partner and Localizer of BRCA2 (PALB2), RAD51 homolog C (RAD51C), RAD51 homolog D (RAD51D), and individuals with Lynch syndrome are susceptible to ovarian cancers." (PMID 37110218, 2023). "Poly (ADP-ribose) polymerase (PARP) inhibitors has demonstrated in their effective management of BRCA1/BRCA2 mutant cancers, most notably in breast and ovarian cancers." (PMID 37190285, 2023). "Phase III trials confirmed the synergized efficacy of antiangiogenic agents combined PARPi in BRCA1/2 wildtype, especially HRD (-) ovarian cancer patients." (PMID 35466318, 2022). "Having established that BRCA1 and BRCA2 expression was correlated with that of other HR genes in ovarian cancers, we sought to develop a targeted and less costly approach to measure BRCA1/2 mRNA levels in FFPE clinical samples." (PMID 35203410, 2022). "Here we provide strong data showing that NR1D1 is a DDR repressor in ovarian cancer cells as well, but that this regulation occurs through a direct interaction of NR1D1 with both PARP1 and BRCA1." (PMID 34743206, 2022). "In ovarian cancer, CpG islands of many tumor-suppressor genes are hypermethylated, including PTEN, SLIT2, MLH1, RASSF1A, and BRCA1, even in the early stages of the disease." (PMID 35269636, 2022). "We also explored the utility of NGS-based detection of BRCA1/2 LGR in guiding the treatment of breast and ovarian cancer patients." (PMID 36147908, 2022). "The clinical utility of positive findings in DNA damage-repair (DDR) genes BRCA1 and BRCA2 for the treatment of patients with breast or ovarian cancer is well established." (PMID 35626031, 2022).
ovarian carcinoma (continued). "The results suggested that BRCA1 knockdown counteracted the synergy between Cur and PTX in ovarian cancer cells." (PMID 36703740, 2022). "Current findings suggested implications for the planning of a screening programme for BRCA1 and BRCA2 genes testing in breast and ovarian cancer patients and genetic screening of their relatives." (PMID 35205313, 2022). "However, as no screening tools currently exist even for BRCA1 mutation carriers, who have a 40% lifetime risk of ovarian cancer, we think that developing a screening tool with high sensitivity and negative predictive value in high-risk populations alone would already be a significant step forward." (PMID 35530324, 2022). "In this study, we measured the levels of BRCA1 and BRCA2 mRNA in ovarian cancers and normal fallopian tubes, the organ from which most ovarian cancers originate." (PMID 35203410, 2022). "Since the identification of BRCA1 and BRCA2 genes in the 1990s as the landmarks of hereditary breast and ovarian cancer, human beings enter the era of cancer genetic testing." (PMID 36439508, 2022). "Our work extends these observations by showing that the expression of BRCA1 and BRCA2 genes significantly correlates with that of an additional 12 HR genes in clinical ovarian cancer samples." (PMID 35203410, 2022). "We selected three ovarian cancer cell lines (OVCAR-5, IGROV-1, and A2780) bearing wild-type BRCA1 and knocked down endogenous BRCA1 using lentivirus-based shRNA." (PMID 35517499, 2022). "Several genes have been confirmed to be closely related to the occurrence and progression of ovarian cancer, including SNAI2, VCAM1, BRCA1, MMP2, MECOM, MXS1, PARP1 and so on." (PMID 35090503, 2022). "For instance, BRCA1 and BRCA2 are partially responsible for breast and ovarian cancers, and their SNVs are widely used for cancer diagnosis." (PMID 35743744, 2022). "The exons 11 were the largest in both BRCA1 and BRCA2, covering more than half of the gene coding sequence and containing ovarian cancer cluster regions." (PMID 35406410, 2022). "Another study showed that promoter methylation levels of BRCA1, a key gene involved in DNA repair, were higher in CDDP-resistant ovarian cancer cell lines and that exposure to a demethylating agent sensitized those cells to platinum treatment." (PMID 35740584, 2022). "The extent to which BRCA1 and BRCA2 mRNA levels are regulated in ovarian cancer has remained poorly understood." (PMID 35203410, 2022). "Considering its high performance and accuracy in the classification of variants in BRCA1 and BRCA2, we believe that it could provide sufficient evidence for the localization of pathogenicity in these specific genes and thus contribute to the prognosis and/or diagnosis of breast or ovarian cancer." (PMID 36358902, 2022). "BRCA1 and BRCA2 are the most commonly tested genes in women with epithelial ovarian cancer (EOC) and around 8% of unselected women diagnosed with EOC have a germline pathogenic variant." (PMID 36068545, 2022). "Across 33 cancer types, both BRCA1/2 alterations and HRD-positivity were most prevalent in ovarian cancer (20% and 69%)." (PMID 35681079, 2022). "Promoters of BRCA1 and RAD51C are frequently methylated in ovarian cancer, which results in a “BRCAness” phenotype that confers sensitivity to PARPis." (PMID 36970052, 2022). "Thus, our findings suggest that a combination of PARP inhibitor with SN-38 could cause extensive DNA damage and DNA replication stress, subsequently leading to cancer cell apoptosis, therefore sensitizing BRCA1/2-proficient ovarian cancer cells to PARP inhibitors." (PMID 36267463, 2022). "Following promising results from breast and ovarian cancer, PARP inhibitors in combination with immune checkpoint inhibitors are being investigated for germline mutant BRCA1/2 pancreatic cancer." (PMID 35163129, 2022).
ovarian carcinoma (continued). "Notably, 79% (49 out of 60 patients with ovarian cancer) did not harbor tumor BRCA1 or BRCA2 (tBRCA) mutations, and 53% had a negative HRD status based on the assay from Myriad Genetics, but the clinical benefits of this combination were apparent regardless of tBRCA mutation or HRD status." (PMID 35163621, 2022). "Two breast and ovarian cancer patients harboring NGS-determined BRCA1/2 LGR benefited from PARPi, indicating that NGS-based detection of BRCA1/2 LGR has the potential to guide PARPi treatment." (PMID 36147908, 2022). "In the mid-1990s, genomic sequencing techniques revealed a link between germline PVs in the tumor-suppressor genes BRCA1 and BRCA2 with breast and ovarian cancer." (PMID 35391652, 2022). "The clinical utility of germline genetic testing for BRCA1 and BRCA2 has been established in patients with histories suggestive of hereditary breast and ovarian cancer." (PMID 35626031, 2022). "The advancement of technology revealed the critical role of many genes, such as BRCA1/2 and BARD1, in hereditary and familial breast and ovarian cancers." (PMID 35650591, 2022). "To maximize the likelihood of discovering genetic modifiers of BRCA1/2, we performed WGS on a total of 66 ovarian cancer (OC) patients that were enriched with BRCA carriers." (PMID 35625955, 2022). "Four devices, spanning three therapeutic products, were identified for BRCA1 and BRCA2 for ovarian cancer." (PMID 35689144, 2022). "Similarly, recording “Genetic susceptibility to malignant neoplasm of ovary” (Z15.01) as a single code to document a finding of BRCA1 or BRCA2 does not convey the scope of the risk (as BRCA1 and BRCA2 also increase the risk of cancer of the breasts and other organs)." (PMID 35571025, 2022). "Although BRCA1 and BRCA2 are intimately involved in DNA damage repair, direct links to TGFβ related EMT in ovarian cancer are emerging." (PMID 33590419, 2021). "In this single-center comprehensive study of germline PALB2 PGVs and the CHEK2_1100delC PGV in breast/ovarian cancer, we show a 1% detection rate for PALB2 PGVs, 1.4% for CHEK2_1100delC, and ~7% for BRCA1/2 PGVs." (PMID 34113003, 2021). "In the 316 ovarian cancers in TCGA, BECN1 and BRCA1 were shallow (monoallelic) deleted in 242 (76.6%) and 240 (76%) cases, respectively." (PMID 33670664, 2021). "Germline BRCA1 variants are often associated with young-onset life-limiting grade 3 triple-negative breast cancers, whereas for women ≥60 years with no previous cancer history who develop an epithelial ovarian cancer, BRCA2 variants are more frequently detected." (PMID 34866136, 2021). "In ovarian cancer, there is a single ovarian cancer region: c.1380 to c.4062 (RHR = 0.62; 95% CI, 0.56–0.70; P = 9 × 10− 17) in BRCA1." (PMID 34711195, 2021). "Overall, testing for moderate- or high-penetrance BRCA1/2, RAD51C, RAD51D, BRIP1, and mismatch repair genes for the patients with epithelial ovarian cancer is recommended." (PMID 34207568, 2021). "Since the relevant gene and protein expression of PLA2G7/PAF-AH were detected exclusively in the BRCA1 mutant cell line UWB1.289, PAF-AH can be considered a new biomarker for BRCA1 mutant ovarian cancer, indicating good prognosis." (PMID 34206491, 2021). "PV in 10 PDAC patients with multiple primary tumors affected 3 × BRCA1 and 4 × BRCA2 (all had also developed breast and/or ovarian cancer), 1 × PMS2 and 1 × MLH1/MSH6 (both developed colon cancer), and 1 × CDKN2A (diagnosed with melanoma)." (PMID 34503238, 2021). "These inhibitory effects on PARP activity were significantly correlated to their cytostatic effects on UWB1.289, UWB1.289 + BRCA1, OVCAR-3 and SKOV-3 human ovarian cancer cells." (PMID 34440232, 2021).